OR4F29 (olfactory receptor family 4 subfamily F member 29)
Description:
Odorant receptor.
Synonyms: OR7-21
Gene: Protein-coding gene on chromosome 1 (450,740 to 451,678, reverse strand). Ensembl gene ENSG00000284733.
Subcellular location: Cell membrane
Pathways (Reactome):
Sensory Perception: Expression and translocation of olfactory receptors
Gene Ontology:
Molecular function: protein binding; olfactory receptor activity; G protein-coupled receptor activity
Biological process: detection of chemical stimulus involved in sensory perception of smell; G protein-coupled receptor signaling pathway
Cellular component: plasma membrane; membrane
Homologues: Orthologues: rat Or4f7 (83% identical), rat Or4f7c (82% identical), mouse Or4f7 (82% identical). Paralogues in human: OR4F16 (100% identical), OR4F3 (100% identical), OR4F21 (99% identical), OR4F15 (71% identical), OR4F6 (67% identical), OR4F4 (57% identical), OR4F5 (57% identical), OR4F17 (56% identical), OR4K5 (53% identical), OR4K17 (53% identical), OR4K15 (51% identical), OR4K1 (51% identical), and 116 more.
Diseases named in the same sentence as OR4F29 in open-access papers:
OR4F29 is named in the same sentence as 1 disease in open-access papers, as found by Europe PMC text mining. Sharing a sentence is not in itself a finding about the gene and the disease.
OR4F29 shares sentences with these, for which no sentence is quoted: tumor (1 paper).